INS (insulin)
Diseases named in the same sentence as INS in open-access papers (continued):
Sharing a sentence is not in itself a finding about the gene and the disease.
Obesity (continued). "The association between increased salivary insulin levels and obesity or overweight in children was found in three studies rated as having high-quality evidence and three with a low-moderate level." (PMID 40565251, 2025). "In populations with obesity, irisin levels are positively associated with muscle mass and resting energy expenditure but negatively associated with body fat percentage, insulin resistance, and triglyceride levels." (PMID 41373506, 2025). "Research suggests that its polyphenolics modulate adipogenesis, improve insulin sensitivity, and reduce oxidative stress and inflammation—key pathways implicated in obesity‐related metabolic dysfunction." (PMID 40666824, 2025). "Evidence suggests that obesity and a surplus of adipose tissue support cancer growth through immune dysregulation, chronic inflammation, and increased insulin signaling, thereby reinforcing the causal link." (PMID 40756563, 2025). "Pancreatic fibrosis, islet inflammation, and loss of β-cell mass cause impaired insulin secretion, while concurrent insulin resistance - exacerbated by obesity, infection, or corticosteroid use - is increasingly recognised in the modern CF population." (PMID 41439084, 2025). "Their complex chemical composition enables synergistic effects on insulin sensitivity, lipid metabolism, inflammation, and OS—all of which represent key pathways implicated in DM, obesity, NAFLD, AS, and thyroid disorders." (PMID 41199858, 2025). "By tissue-specific gene KO in mice, we identify the histone chaperone HIRA as a novel epigenomic regulator of insulin sensitivity and obesity-associated adipose tissue expansion." (PMID 40196683, 2025). "Under basal conditions in obesity, IL-6 is primarily derived from adipose tissue, where it contributes to a chronic pro-inflammatory state linked to impaired insulin signaling." (PMID 41002965, 2025). "Obesity-related desensitization towards insulin action in adipose tissue is commonly associated with a reduced expression of the INSR, which was not the case in GHR-KO subcutaneous adipose tissue." (PMID 41125144, 2025). "This review focuses on the actions of EPO in WAT and the liver, as most studies examining EPO in the context of obesity-associated inflammation in insulin-sensitive organs have concentrated on these two metabolic tissues." (PMID 40697664, 2025). "In contrast, bimagrumab, a fully human monoclonal antibody that inhibits activin type II receptors, results in significant fat mass loss, increased lean mass, and improved insulin sensitivity in people with obesity and T2D." (PMID 40171198, 2025). "The chronic low-grade inflammation, altered adipokine secretion, and ectopic lipid accumulation associated with obesity collectively contribute to the deterioration of insulin sensitivity and β-cell function." (PMID 40430501, 2025). "Natural compounds have shown significant potential in improving the metabolic dysregulation associated with T2DM and obesity by regulating glucose and lipid metabolism, alleviating oxidative stress, and enhancing insulin sensitivity." (PMID 40004938, 2025). "Allobaculum, a genus of SCFA-producing bacteria, has been associated with improvements in obesity, such as reduced body weight and diminished low-grade inflammation, as well as better insulin resistance management." (PMID 40136712, 2025). "Butyrate and propionate are particularly noted for enhancing insulin sensitivity in muscle and fat tissues, reducing blood glucose levels, and aiding obesity prevention and T2D risk reduction." (PMID 41268546, 2025). "Key genetic variations, including SNPs in FTO (fat mass and obesity-associated) and PPARγ (peroxisome proliferator-activated receptor gamma), play significant roles in metabolic regulation, affecting insulin sensitivity, lipid metabolism, and energy balance." (PMID 40004938, 2025). "Data show that during obesity, the promoter region of insulin-sensitive genes has reduced acetylation, which is linked to metabolic dysfunction." (PMID 40868241, 2025).
Obesity (continued). "Magnesium is fundamental to glucose metabolism and insulin action, and deficiency is frequent in obesity due to inadequate intake and increased renal excretion." (PMID 41305652, 2025). "An elevated F/B ratio is usually positively correlated with obesity, metabolic disorders, and other diseases, and is associated with increased heat extraction from food, fat deposition, lipogenesis, and impaired insulin sensitivity." (PMID 41244340, 2025). "By managing insulin levels, physical activity can contribute to weight control and reduce the risk of cardiovascular diseases associated with obesity and diabetes." (PMID 40108925, 2025). "Its role in glucose and energy balance is reiterated by SHIP2 deficiency in mice, which causes hypoglycemia, insulin-induced Akt activation, and resistance to high-fat diet-induced obesity." (PMID 40141412, 2025). "Increased consumption of sugar and sweetened beverages disrupts blood sugar and insulin balance, leading to metabolic imbalances, overweight and obesity which are linked to various cancer sites addressed within this study." (PMID 40630609, 2025). "Our findings not only identify HIRA as an epigenomic regulator of insulin sensitivity, lipogenesis, and obesity-associated adipose expansion, but also reveal a novel mechanism by which HIRA regulates transcription." (PMID 40196683, 2025). "The resulting cycle of dopaminergic dysfunction, insulin dysregulation, and metabolic imbalance forms a self-reinforcing loop that accelerates obesity risk." (PMID 41279682, 2025). "Fourth, poor sleep impacts insulin sensitivity and promotes weight gain and obesity, both of which are associated with higher risks of cancers, including breast, colorectal, and prostate cancer." (PMID 40072785, 2025). "Hyperinsulinemia, marked by dysregulated insulin secretion and/or insulin clearance, is commonly associated with obesity and metabolic dysregulation manifested in T2D." (PMID 40940776, 2025). "miR‐375 and other miRNAs such as hsa‐miR‐130b‐3p and hsa‐miR‐142‐5p are linked to obesity and insulin secretion modulation." (PMID 40551726, 2025). "Our results align with the notion that reduced PPAR-γ activity in adipocytes can mitigate obesity-associated metabolic dysfunction and improve systemic insulin sensitivity." (PMID 40968148, 2025). "The mechanisms underlying obesity-related cancers are active areas of research, but likely involve chronic inflammation, insulin resistance, and hormonal alterations caused by excess adipose tissue." (PMID 41041606, 2025). "Obesity also elevates cancer risk and worsens prognosis by altering levels of insulin, insulin-like growth factor 1, leptin, adiponectin, steroid hormones, and cytokines." (PMID 40864791, 2025). "We found that a complete absence of maternal Sst expression increased the risk of male offspring to diet-induced obesity and severe insulin and leptin resistance." (PMID 40066865, 2025). "The psPRS for Obesity from soft-clustering was also nominally associated with a higher incidence of insulin initiation." (PMID 39531041, 2025). "Approximately 10–25% of obese people are metabolically healthy due to preserved insulin sensitivity and are more resistant to obesity-associated metabolic disorders." (PMID 40004620, 2025). "In obese and hyperglycemic mice, the administration of anti-resistin antibody reduced glucose level and improved insulin sensitivity, indirectly suggesting that elevated resistin levels played a causative role in the high risk of obesity-related T2DM." (PMID 39812542, 2025). "Lipid metabolism is coordinated by insulin signaling, which helps explain why diseases associated with dysfunctional insulin signaling, including obesity and T2D, are also characterized by dysregulated lipid metabolism." (PMID 41226287, 2025). "GLP‐1RAs were linked to a lower risk of 10 out of 13 obesity‐associated cancers (OACs) compared to insulin, suggesting a potential preventive effect against cancer." (PMID 39980820, 2025).
Obesity (continued). "FXR activation in both the liver and intestines has been shown to inhibit hepatic lipogenesis, improve insulin sensitivity, and enhance energy expenditure, ultimately contributing to the mitigation of obesity risk." (PMID 41007736, 2025). "In central nervous system (CNS), IR causes obesity because appetite is controlled by the action of insulin in the CNS and neuronal insulin signaling is required for both body weight control and glucose homeostasis." (PMID 41473239, 2025). "When dietary protein is inadequate during adolescence, it has long-term consequences in male rats, leading to an obesity phenotype associated with insulin resistance and hypothalamus-pituitary-gonadal axis and testosterone disruption." (PMID 41154756, 2025). "It has been suggested that obesity can contribute to cancer risk by causing chronic inflammation and increased insulin, insulin-like growth factor, and sex hormones." (PMID 41038346, 2025). "Obesity causes various health risks, including dyslipidemia, high blood pressure, impaired insulin sensitivity, and disrupted glucose regulation." (PMID 40888131, 2025). "Consistent with this, the suppression of GATA3 has been shown to improve the adipogenesis process, restore insulin sensitivity, and reduce obesity-associated inflammation in patients with obesity." (PMID 40423250, 2025). "We uncover an insulin‐dependent mechanism connecting low D2 receptor function to obesity risk, more prominent in males than in females." (PMID 41279682, 2025). "Evidence suggests that interrupting the inflammatory response caused by obesity allows insulin sensitivity to be restored." (PMID 41300428, 2025). "Obesity is associated with increased insulin‐stimulated brain glucose uptake (BGU) which is opposite to decreased GU observed in peripheral tissues." (PMID 40926735, 2025). "A wealth of studies highlight the efficacy of fasting in the prevention of obesity, which goes beyond thermogenesis activation and weight loss, as fasting also provides numerous health benefits by improving insulin sensitivity and metabolic alterations." (PMID 41011119, 2025). "miRNAs function in many biological processes associated with obesity, such as energy metabolism, adipose tissue homeostasis, inflammation, insulin resistance, and cellular stress by regulating gene expression at the post-transcriptional level." (PMID 40565979, 2025). "Improvements in fasting glucose, HbA1c, and insulin sensitivity measures further validate semaglutide’s efficacy and safety as a treatment option for obesity-associated prediabetes." (PMID 41212412, 2025). "A decrease of 0.30 standard deviations (SD) of BMI in adolescents with obesity is linked to a substantial reduction in intrahepatic and intramuscular fat deposition, with an increase in insulin sensitivity." (PMID 40195232, 2025). "It is closely linked to obesity, which is a key risk factor for hypertension through mechanisms such as insulin resistance and inflammation." (PMID 41398253, 2025). "A relatively short-term (4-month) “well-formulated KD” in children aged 8–18 years with obesity, IR, and MS leads to significant weight loss, improved insulin sensitivity, and regression of MS in a significant portion of the patients." (PMID 40277805, 2025). "Clearly, further studies are needed to disentangle the role of brain insulin responsiveness and inflammation in the development of obesity and associated diseases, as subclinical low-grade inflammation is well known to affect metabolic regulation." (PMID 39984682, 2025). "Integrated protein-metabolite network analysis identified OSBPL10, CUL2, and PRTN3 as potential regulators of lipid metabolism and insulin resistance, offering insights into obesity-associated metabolic dysfunction." (PMID 40822952, 2025). "Obesity-associated inflammation disrupts pancreatic β-cell function, but the immune-derived signals that directly regulate insulin secretion remain incompletely defined." (PMID 41278909, 2025).
Obesity (continued). "For instance, in a diet-induced-obesity mouse model, the brains of 16-week-old mice exhibited opening of the mPTP, loss of mitochondrial membrane potential, and apoptosis, while insulin supplementation corrected these dysfunctions." (PMID 41465437, 2025). "The purpose of this study is to assess the longitudinal associations between UPF consumption and prediabetes and obesity in young adults, using glucose and insulin measurements, body composition, and diet assessment over four years of follow-up." (PMID 40630535, 2025). "Antioxidant-rich diets, including the Mediterranean diet, are strongly associated with improved metabolic health, reduced obesity rates, and enhanced insulin sensitivity." (PMID 40002389, 2025). "Patients with leptin receptor mutations experience an extremely early onset of obesity, which has a direct effect on hyperphagia, insulin sensitivity, glucose intolerance, metabolic disorders, and recurring infections." (PMID 41009702, 2025). "The anti-obesity effects of IF were evident as indicated by body mass loss, visceral fat reduction and improved glucose and insulin tolerance between ADF and AL groups." (PMID 41301432, 2025). "HFD-induced obesity also downregulated circadian rhythm genes associated with insulin sensitivity and adipogenesis in mesenchymal stem cells, but exercise reversed this effect and increased expression of these genes." (PMID 40522819, 2025). "At the same time, exercise stimulates the secretion of leptin, insulin and other hormones and mediates the uptake of blood sugar and blood lipids by skeletal muscle, thus reducing the risk of obesity." (PMID 41048303, 2025). "Recent research has linked improvements in insulin sensitivity in diet-induced obesity (DIO) mice and Venezuelan hookworm infections to microbial community alterations, notably an increase in lactobacilli and decreased intestinal permeability." (PMID 41268546, 2025). "One well-documented hallmark of obesity is the expansion of adipose tissue, a highly active endocrine organ secreting numerous hormones that regulate critical processes such as metabolism, insulin sensitivity, appetite control, and vascular function." (PMID 40548377, 2025). "On the other hand, the dysregulation of the Akt signaling pathway, which operates downstream of the insulin signaling, has been implicated in altered glucose metabolism, which is a key aspect of obesity-related metabolic dysfunction." (PMID 40825507, 2025). "Massive obesity with preserved insulin sensitivity is also observed in leptin-deficient (ob/ob) male and female mice overexpressing the mitochondrial membrane protein, mitoNEET." (PMID 37961647, 2025). "Obesity is associated with a wide range of pathophysiological changes in many cell types, tissues, and organs, including systemic inflammation, insulin resistance, and alterations in hormonal signaling." (PMID 40862085, 2025). "By contrast, HFD-only mice exhibited elevations in aromatic amino acids and BCAAs relative to controls, a pattern compatible with early obesity-associated adaptation while insulin signaling remained partially preserved." (PMID 41002949, 2025). "In a recent publication including 541 Ghanaians with adult-onset diabetes mellitus, subgroups including obesity-related (73%), insulin-resistant (5%) and insulin-deficient (7%), age-related (10%) and autoimmune-related (5%) were reported." (PMID 39913381, 2025). "The loss of intestinal GATA4 prevents diet-induced obesity, promotes insulin sensitivity, and protects against diet-induced hepatic steatosis in mice." (PMID 41190635, 2025). "Poor eating habits, along with other environmental factors, can lead to obesity in genetically predisposed individuals, with the proliferation of adipocytes, increased insulin resistance, and implicit changes in the intestinal microbiome." (PMID 41441034, 2025).
Obesity (continued). "Higher insulin doses increase the risk of hypoglycaemia, which can lead to maladaptive eating behaviours that contribute to the onset of obesity." (PMID 40130476, 2025). "A reverse association between the adiponectinemia and obesity (particularly the abdominal), as well as a strong positive correlation between the adiponectin levels and the insulin sensitivity, has been described." (PMID 41373994, 2025). "In equids, various correlations exist among circulating inflammatory cytokines, equine metabolic syndrome (EMS), obesity, and insulin concentrations, with ponies at increased risk for insulin dysregulation (ID)." (PMID 40048369, 2025). "Another study showed that in HFD-induced obesity in mice, the gut microbiome affects neutrophil infiltration-associated inflammation of visceral adipose tissue and insulin sensitivity." (PMID 39861371, 2025). "The development of insulin resistance is associated with a variety of factors, including obesity, genetic background, and defects in insulin signaling pathways." (PMID 40520185, 2025). "Together, these findings demonstrate that low striatal D2 receptor density predisposes male mice to an obesity-like phenotype through early dopaminergic dysfunction that precedes weight gain and is later compensated by insulin hypersensitivity in the brain." (PMID 41279682, 2025). "This study intergartes clinical dosing evidence with mechanistic investigation to identify and validate the 3:1 berberine-wogonin ratio as a dual targeting strategy against HIF-1α/HIF-2α pathways, effectively ameliorating obesity-associated insulin resistance." (PMID 41039626, 2025). "Circadian misalignment in individuals with genetic predispositions to obesity disrupts the release of key metabolic hormones, such as leptin and insulin, impairing hunger regulation and fat storage." (PMID 40024983, 2025). "Dysregulated HPA function also impacts leptin and insulin resistance pathways, further impairing energy balance and exacerbating cognitive deficits in obesity and air pollution exposure-linked conditions." (PMID 41515969, 2025). "Multi-tissue transcriptomic analyses highlighted gene expression changes and pathways associated with insulin-sensitive obesity." (PMID 37961647, 2025). "The mechanisms by which obesity causes hypertension include alterations in adipose-derived hormones, insulin resistance, sympathetic nervous system overactivation, stimulation of the renin-angiotensin-aldosterone system, and renal sodium retention." (PMID 39963158, 2025). "Central to these processes are disruptions in the regulation of insulin signaling, adipogenesis, lipid metabolism, and inflammatory responses, all of which contribute to the onset of obesity and its associated complications." (PMID 40218884, 2025). "Late eating habits have been associated with adverse health outcomes, such as an increased risk of overweight/obesity, glucose intolerance, and reduced insulin secretion." (PMID 40787788, 2025). "A hallmark of insulin-resistant conditions, including obesity, hepatic steatosis and type 2 diabetes, is the persistent and excessive reliance on FFA as the primary energy source for the liver and muscles, at the expense of glucose utilization." (PMID 40219026, 2025). "STAT1 emerges as a pivotal player in the regulation of mitochondrial function, insulin sensitivity, and obesity-associated inflammation." (PMID 40423250, 2025). "One suggests that elevated maternal glucose levels lead to fetal hyperglycaemia, which in turn stimulates the fetal pancreas to produce insulin, promoting fetal growth and increasing the risk of obesity later in life." (PMID 40523944, 2025). "Obesity is associated with chronic, low-grade inflammation in these tissues, where inflammatory cytokine signaling disrupts insulin pathways, impairing glucose uptake and promoting uncontrolled lipolysis." (PMID 41305576, 2025).